TGILR (TGF-beta induced TARBP2 interacting lncRNA)
Synonyms: AL590004.3; RP1-140K8.5
Gene: Long non-coding RNA gene on chromosome 6 (3,893,029 to 3,913,718, reverse strand). Ensembl gene ENSG00000260604.
Diseases named in the same sentence as TGILR in open-access papers:
TGILR is named in the same sentence as 6 diseases in open-access papers, as found by Europe PMC text mining. Sharing a sentence is not in itself a finding about the gene and the disease. The quoted sentences say what the papers report.
gastric cancer (2 papers, 2024). A primary or metastatic malignant neoplasm involving the stomach. "Clinical analysis showed that TGILR overexpression showed a significant correlation with lymph node metastasis and poor survival and was an independent prognostic factor in gastric cancer (GC)." (PMID 38806480, 2024). "Furthermore, the secretion of TGF-β by CAFs upregulates the TGILR levels within gastric cancer cells, exacerbating their proliferative capacity." (PMID 39717771, 2024). "SMAD3, phosphorylated by TGF-β, translocates to the nucleus, binding to the TGILR promoter and promoting its transcription; TGILR sustains TARBP2 protein stability, hastening TARBP2-mediated degradation of miR-1306 and miR-33a, and upregulating TCF4, thereby advancing gastric cancer progression." (PMID 39717771, 2024). "Additionally, we identified that the TGFbeta/TGILR axis was involved in the crosstalk between CAF and gastric cancer cells." (PMID 38806480, 2024).
breast carcinoma (1 paper, 2024). "Consistently, chip-seq analysis regarding SMAD3 in lung cancer (NCL-H441) and breast cancer cell lines (HCC1954, MDA-MB-231) together showed that there were 3 SMAD3 binding peaks in the promoter region of TGILR." (PMID 38806480, 2024).
lymph node metastasis (1 paper, 2024). "TGILR overexpression is clinically associated with lymph node metastasis and poor survival, and plays an oncogenic role in GC." (PMID 38806480, 2024). "Herein, we show that TGILR overexpression is clinically associated with malignant progression, lymph node metastasis, and is an independent prognostic factor for survival in GC patients." (PMID 38806480, 2024).
cancer (1 paper, 2024). A tumor composed of atypical neoplastic, often pleomorphic cells that invade other tissues. "The induction of TGILR expression by rhTGFbeta protein is widely present in different GC cell lines and human cancer cell lines, indicating that the regulation of TGILR expression by TGFbeta is highly conserved across human tissues." (PMID 38806480, 2024). "More importantly, the induction of TGILR expression by TGFbeta signaling is highly conserved in different human cancer cell lines, indicating that TGILR may play an important role in cancer." (PMID 38806480, 2024). "In this study, we discovered a novel TGFbeta-induced lncRNA, termed TGILR, whose function in cancer remains unknown to date." (PMID 38806480, 2024). "Notably, the induction of the lncRNA TGILR by the canonical TGFbeta/SMAD3 signaling is highly conserved in cancer." (PMID 38806480, 2024). "The biological role of lncRNA TGILR remains unknown in cancer." (PMID 38806480, 2024). "TGILR expression was directly activated by the canonical TGFbeta/SMAD3 signaling axis, and this activation is highly conserved in cancer." (PMID 38806480, 2024). "To investigate the regulatory role of CAF infiltration on TGILR expression, we isolated and obtained NF and corresponding CAF cells from cancer tissue and adjacent tissues of the same donor." (PMID 38806480, 2024). "The biological function of TGILR in cancer has not been reported yet." (PMID 38806480, 2024).
tumor (1 paper, 2024). "In addition, a subcutaneous xenograft tumor mouse model of TGILR_KD was established to determine the biological role of TGILR knockdown on GC cell growth." (PMID 38806480, 2024).
TGILR also shares sentences with these, for which no sentence is quoted: lung carcinoma (1 paper).